TLR9 (toll like receptor 9)
Diseases named in the same sentence as TLR9 in open-access papers (continued):
Sharing a sentence is not in itself a finding about the gene and the disease.
prostate carcinoma (continued). "To further understand this apparent disparity, we have investigated the effect of TLR9 stimulation on prostate cancer progression in an immune-competent, syngeneic orthotopic mouse model of prostate cancer." (PMID 38201300, 2024). "This study demonstrated that systemic TLR9 stimulation negatively regulates prostate cancer tumorigenesis and highlights TLR9 agonists as a useful therapeutic for the treatment of prostate cancer." (PMID 38201300, 2024). "In this study, we provided evidence that TLR9 activation via CPG-1668 treatment markedly suppressed prostate tumorigenesis in an orthotopic in vivo mouse model of prostate cancer." (PMID 38201300, 2024). "It will be informative for future studies to test various CPG-ODN compounds also in orthotopic prostate tumor models to fully evaluate the effects of TLR9 stimulation on prostate cancer pathogenesis." (PMID 38201300, 2024). "Toll-like receptors (TLRs) and immunity have a direct role in prostate cancer pathogenesis, but TLR9 has been reported to contribute to both the progression and inhibition of prostate tumorigenesis." (PMID 38201300, 2024). "Another reported effect of TLR9 agonism in prostate cancer has been the direct TLR9-dependent killing of tumor cells in some settings." (PMID 38201300, 2024). "To address these discrepancies, we utilized a syngeneic model of prostate cancer to examine the impact of TLR9 stimulation on the growth of orthotopic prostate tumors." (PMID 38201300, 2024). "In vitro stimulation of TLR9 in prostate cancer lines enhances the expression of protumorigenic and pro-proliferative genes; however, the response of RM1 cells to CPG-1668 specifically has not been reported." (PMID 38201300, 2024). "Multiple studies report that high expression of TLR9 or its stimulation with CPG-ODNs in prostate cancer cells increases the expression of invasive and metastatic genes." (PMID 38201300, 2024). "Autophagy can be triggered by CpG-ODNs in tumor cell lines (e.g., colon, breast, and prostate cancers) in a TLR9-dependent manner." (PMID 35651701, 2022). "Autophagy can be triggered by CpG-oligodeoxynucleotides in tumor cell lines (e.g.: colon, breast, and prostate cancers) via a TLR9-dependent manner." (PMID 35551547, 2022). "TLR9 expression in prostate cancer cells promotes immune evasion through LIF (an IL-6 type cytokine and STAT3 activator) mediated polymorphonuclear MDSC amplification and activation." (PMID 36365103, 2022). "Another in vitro study suggested that TLR9 agonists can stimulate prostate cancer invasion by increasing MMP13 activity." (PMID 33336901, 2021). "A short period of time later, two other groups demonstrated TLR9 is critical to the formation of CSCs in prostate cancer and GSCs." (PMID 32843056, 2020). "TLR9 expanded stem-like androgen-independent prostate cancer cells through NF-κB and STAT3 activation, which in turn upregulated the expression of stemness-associated genes, including NKX3.1, KLF-4, BMI-1, and COL1A1." (PMID 28116318, 2016). "In prostate cancer cell line PC-3, gene silencing of Toll-like receptor-9 (TLR9), reversed migration and invasiveness and resulted in downregulation of a number of genes including LURAP1L." (PMID 27096627, 2016). "Doses and uptake of CpG-siRNA by TLR9+ human prostate cancer cells were comparable to our previous observations in blood cancer models." (PMID 26046794, 2015). "To elucidate TLR9-mediated transcriptional regulation, we focused on two key prostate cancer stem cell-related genes: NKX3.1 and KLF-4." (PMID 26046794, 2015). "In this study, we investigated the expression and clinical significance of TLR9 in prostate cancer tissue and explored the role of TLR9 signaling network in the migration and invasion of prostate cancer." (PMID 26087186, 2015). "More recent studies found that TLRs, such as TLR9, are expressed by solid tumors including prostate cancers." (PMID 26046794, 2015).
prostate carcinoma (continued). "Our data presented here provide important clues for elucidation of the mechanism of TLR9 in invasion and migration of prostate cancer and for development of new anticancer strategies." (PMID 26087186, 2015). "TLR9 expression in prostate cancer cells creates an opportunity to use this receptor as a target for the delivery of therapeutic molecules, such as CpG-siRNA conjugates." (PMID 26046794, 2015). "Our results align with earlier reports demonstrating elevated TLR9 expression in prostate cancers with higher Gleason scores and in the cell lines established from more advanced tumor stages such as PC3 or DU145." (PMID 26046794, 2015). "We demonstrate that TLR9/NF-κB/STAT3 signaling axis operates in prostate cancer cells to promote expression of tumorigenic and stem cell-related genes." (PMID 26046794, 2015). "TLR9 expression in prostate cancer propagating cells creates an opportunity to use this receptor as a target for the delivery of therapeutic molecules, such as CpG-siRNA." (PMID 26046794, 2015). "We found that TLR9 expression is essential for prostate cancer cells ability to differentiate into adipocytes or osteoblasts." (PMID 26046794, 2015). "Overall, in all tested prostate cancer models, high TLR9 expression correlated with tumor engraftment and growth." (PMID 26046794, 2015). "Here, we demonstrate that triggering of the innate immune receptor, Toll-like Receptor 9 (TLR9), in androgen-independent prostate cancer cells initiates signaling cascade leading to increased tumor growth and progression." (PMID 26046794, 2015). "The notion of stem cell phenotype reversibility find some support in our findings that forced expression or silencing of TLR9 can affect tumor-propagating potential of prostate cancer cells." (PMID 26046794, 2015). "The TLR9+ prostate cancer cells have increased both clonogenic potential and the ability to differentiate into osteoblast- or adipocyte-like cells similarly as bone marrow mesenchymal stem cells." (PMID 26046794, 2015). "Previous studies reported that prostate cancer cells express innate immune receptors, such as TLR9, normally restricted to the hematopoietic cell lineage." (PMID 26046794, 2015). "To explore the function of TLR9 in prostate cancer, we silenced TLR9 expression in PC-3 cells with transfection of TLR9 siRNA." (PMID 26087186, 2015). "Global gene profiling provides the data about altered gene expressions of TLR9 signaling network in prostate cancer." (PMID 26087186, 2015). "Using limited dilution/serial transplantation experiments, we show that TLR9 is essential for prostate cancer cells' potential to propagate and self-renew in vivo." (PMID 26046794, 2015). "Together with our prior results, these observations support the notion that TLR9 expression in prostate cancer cells promotes tumor-propagating and stem cell-like phenotype, which is likely responsible for enhanced aggressiveness." (PMID 26046794, 2015). "In this study, we constructed TLR9-silenced PC-3 cells as a model to investigate the function of TLR9, and the results showed that silence of TLR9 inhibited migration and invasion of prostate cancer." (PMID 26087186, 2015). "Recently, data concerning the overexpresion of TLR9 in a wide variety of cancers including prostate cancer are starting to accumulate." (PMID 26087186, 2015). "Overall, our findings suggest that TLR9-mediated siRNA delivery targets prostate cancer-propagating cells, thereby halting tumor progression." (PMID 26046794, 2015). "EGCG suppresses proinflammatory cytokines and chemokines induced by Toll-like receptor 9 agonists in prostate cancer cells." (PMID 26177797, 2015). "The IPA analysis of our RNAseq data suggested NF-κB/RELA and STAT3 as top mediators of TLR9-dependent gene expression in prostate cancer cells." (PMID 26046794, 2015).
prostate carcinoma (continued). "Our study reconciles these observations as it identifies a novel function of TLR9 signaling in cancer cells and underscores the role of inflammation in prostate cancer progression." (PMID 26046794, 2015). "Overcoming cancer cell self-renewal and tumor-propagating potential by targeted inhibition of TLR9 signaling can provide therapeutic strategy for late-stage prostate cancer patients." (PMID 26046794, 2015). "Our study highlighted the mechanism of TLR9 in regulation of migration and invasion of prostate cancer and identified the new targets for anticancer therapeutic intervention." (PMID 26087186, 2015). "Previous studies reported expression of the innate immune receptor TLR9 in human prostate cancer cells." (PMID 26046794, 2015). "Previous in vitro studies suggested that TLR9 promotes prostate cancer cell proliferation and/or invasiveness." (PMID 26046794, 2015). "We demonstrate for the first time that TLR9 expression promotes tumor-propagating potential of prostate cancer cells in vivo." (PMID 26046794, 2015). "TLR9 expression in prostate cancer cells has similarly been found to enhance invasiveness via induction of MMP-13 in vitro." (PMID 25101092, 2014). "TLR9 expression was also statistically significantly increased in prostate cancer epithelium and stroma, compared with the same cellular compartments in benign hyperplasia, especially in the most poorly differentiated forms." (PMID 25101092, 2014). "In the Cox regression analysis, high TLR9 expression was an independent marker of poor prognosis in prostate cancer." (PMID 23761830, 2013). "Cytoplasmic TLR9 expression, Gleason score 8–10 and pT3a-pT3b, were statistically significant factors in prostate cancer-specific progression-free survival." (PMID 23761830, 2013). "This should be answered via research in pre-clinical prostate cancer models, using prostate cancer cells with manipulated TLR9 expression levels." (PMID 23761830, 2013). "Based on the results of this study, high TLR9 expression is an independent marker of poor prognosis in prostate cancer." (PMID 23761830, 2013). "If TLR9 is significant in the pathophysiology of prostate cancer, the mechanism by which it promotes prostate cancer must be determined." (PMID 23761830, 2013). "We have previously demonstrated that the level of TLR9 expression is higher in prostate cancer than in benign hyperplasia." (PMID 23761830, 2013). "It is now well established that TLR9 is also expressed in various cancer cells, including breast, brain, ovarian, gastric, lung and prostate cancer cells." (PMID 21929816, 2011). "Notably, TLR9 levels were significantly higher in both the epithelial and stromal compartments of prostate cancer compared with benign prostatic hyperplasia, with the most pronounced expression observed in poorly differentiated tumors." (PMID 41601666, 2026). "A clinical study has confirmed TLR9 expression in prostate cancer specimens." (PMID 41601666, 2026). "Since bone metastasis is one of the most significant pathways in prostate cancer, we hypothesize that TLR‐9 may promote the bone metastasis of prostate cancer via stimulating MDSCs, and it depends on further studies to verify." (PMID 39947253, 2025). "Activated TLR9, by CpG DNA in infection-induced cancers, or by tumor-derived DAMPs, induces NF-κB activation, resulting in immune cell infiltration, increased proliferation, and reduced apoptosis, as has been demonstrated in human prostate cancer." (PMID 38850110, 2024). "Overall, the apparent dual function of TLR9 to act in immune cells (to promote antitumor immunity) or in cancer cells (to promote tumor growth and progression) will likely govern the outcomes of therapeutic TLR9 stimulation in various cancer models, including prostate cancer." (PMID 38201300, 2024).
prostate carcinoma (continued). "Prostate cancer and its interaction with the host immune system is immensely complex, so the function of TLR9 in immune cells to negatively regulate prostate tumor pathogenesis could be considered in the development of novel prostate cancer therapeutics." (PMID 38201300, 2024). "In summary, we have identified that stimulating TLR9 via the class B ODN CPG-1668 may be a possible therapeutic option for prostate cancer." (PMID 38201300, 2024). "Additionally, a subcutaneous prostate cancer model utilizing NOD SCID gamma mice showed that tumor growth correlated with the expression of TLR9 in tumor cells." (PMID 38201300, 2024). "However, the up‐regulation in TLR9 in oesophageal adenocarcinoma, squamous cell carcinoma of the tongue and prostate cancer is related to the more aggressive form of the disease and the dismal outcome." (PMID 33336901, 2021). "Toll-like receptor 9 has been shown to promote prostate cancer progression." (PMID 29928275, 2018). "Importantly, TLR9 cytoplasmic immunostaining is positive in the majority of patients (66.7% strongly and 31.7% weakly positive) in prostate cancer cells." (PMID 29928275, 2018). "Moreover, TLR9 has been shown to be essential for propagation and self-renewal of prostate cancer cells through NF-κB/RELA and STAT3 pathways, and TLR9-positive tumors have a unique gene profile that associate with inflammation and stem cells." (PMID 29928275, 2018). "Next, Cox multivariate progression- free survival analysis was carried out to examine whether TLR9 expression was an independent factor for predicting prognosis in prostate cancer." (PMID 26087186, 2015). "In addition to immune cells, TLR9 is also expressed in various human cancer cells, including prostate cancer." (PMID 26087186, 2015). "Furthermore, low expression or silencing of TLR9 limits the clonogenic potential and mesenchymal stem cell-like properties of LNCaP- and PC3-derived prostate cancer cell variants." (PMID 26046794, 2015). "Finally, we demonstrate the feasibility to use TLR9-mediated siRNA delivery for targeting prostate cancer-propagating cells in vivo, thereby halting tumor progression." (PMID 26046794, 2015). "However, to our knowledge this is the first report of TLR9′s role in promoting prostate cancer cells' self-renewal and tumor-propagating potential." (PMID 26046794, 2015). "To further explore TLR9 signaling network in regulation of migration and invasion of prostate cancer, we focused on analyzing the interactions of genes which might be involved in migration and invasion." (PMID 26087186, 2015). "We employed whole transcriptome profiling to dissect the TLR9's role in prostate cancer cells." (PMID 26046794, 2015). "Finally, silencing of RELA or STAT3 specifically in TLR9+ tumor-propagating cells inhibits growth of established prostate cancers in vivo." (PMID 26046794, 2015). "However, the mechanism of cellular DNA receptor TLR9 promoting invasion and metastasis in prostate cancer is still unclear." (PMID 26087186, 2015). "We used standard colony/sphere formation assays to verify whether TLR9 expression affects clonogenic potential of prostate cancer cells." (PMID 26046794, 2015). "Furthermore, we demonstrated that high TLR9 expression in prostate cancer is significantly associated with a decreased b-PFS, indicating the prognostic implications of TLR9 in patients with prostate cancer." (PMID 26087186, 2015). "In both LNCaP and PC3 cell variants higher levels of TLR9 expression and activation (by CpG ODN stimulation) correlated with increased mRNA and protein levels of IL-6, an important STAT3 activator and a contributor to prostate cancer progression." (PMID 26046794, 2015). "Targeting of TLR9+ tumor-propagating cells alone or in combination with antiproliferative agents has potential to address an unmet need for treatment of patients with advanced and poorly differentiated prostate cancers." (PMID 26046794, 2015).
prostate carcinoma (continued). "Given the similarity between prostate cancer cells and bone marrow mesenchymal stem cells, TLR9+ tumor-propagating cells may play a role in the metastatic tumor spread to bone." (PMID 26046794, 2015). "Further silence of TLR9 inhibited migration and invasion of prostate cancer cells." (PMID 26087186, 2015). "In the current study, we investigated whether inflammatory TLR9 signaling in prostate cancer cells provides a set of molecular targets driving tumor aggressiveness and tumor-propagating potential." (PMID 26046794, 2015). "Finally, bicalutamide, a commonly used hormonal treatment in prostate cancer, increased TLR9 expression in ER-positive breast cancer cells." (PMID 25101078, 2014). "A clinical study demonstrated that TLR9 is expressed in prostate cancer specimens." (PMID 25101092, 2014). "TLR9 stimulation by CpG-ODN plays an important role in prostate cancer invasion." (PMID 25101092, 2014). "Considering the importance of sex hormones in the aggressive behavior of prostate cancer, this effect on TLR9 may also contribute to the explanation." (PMID 23761830, 2013). "There are several possibilities; firstly, TLR9 may promote the spread of prostate cancer by facilitating prostate cancer invasion." (PMID 23761830, 2013). "There were 186 prostate cancer samples available for the evaluation of TLR9 immunoreactivity." (PMID 23761830, 2013). "The aim of this study was to investigate whether expression levels of TLR9 in tumors has prognostic value in prostate cancer." (PMID 23761830, 2013). "Therefore, targeting the TLR9/LIF/STAT3 signaling pathway with oligonucleotide-based inhibitors might offer new immunotherapies to treat prostate cancer." (PMID 41601666, 2026). "Therefore, oligonucleotide-based inhibitors (e.g., CpG-STAT3dODN) targeting TLR9/LIF/STAT3 signaling may offer new opportunities for prostate cancer immunotherapy." (PMID 36365103, 2022). "TLR4 and TLR9 could endow prostate cancer cells the ability to proliferate more aggressively." (PMID 33336901, 2021). "Targeting TLR9 signaling may provide therapeutic strategies for prostate cancer patients." (PMID 29928275, 2018). "Thus, we tested whether upregulation of TLR9 levels will stimulate such properties of prostate cancer cells." (PMID 26046794, 2015). "Considering that TLR9 was significant in predicting poor prognosis of prostate cancer, we speculated the expression of TLR9 was correlated with the capability of invasion and metastasis of prostate cancer cells." (PMID 26087186, 2015). "To assess whether TLR9 contributes to prostate cancer progression, we selected three prostate cancer models: parental LNCaP cells, LNCaP-S17 cells stably expressing IL-6 and PC3-luc cells as representing less or more advanced stages in the progression to androgen-independence, respectively." (PMID 26046794, 2015). "The prostate cancer-specific progression-free survival (b-PFS) rate of patients with low TLR9 expression (N = 49) was significantly larger than that of patients with high TLR9 expression (N = 29), suggesting the high expression of TLR9 in prostate cancer indicates poor prognosis." (PMID 26087186, 2015). "Therefore, targeting TLR9+ tumor-propagating cells alone or in combination with expanding panel of antiproliferative agents, can address an unmet need for treatment of patients with advanced and poorly differentiated prostate cancers." (PMID 26046794, 2015). "Moreover, the high TLR9 expression was an independent marker of poor prognosis in prostate cancer." (PMID 26087186, 2015). "The prostate cancer-specific progression-free survival rate was significantly longer for patients whose tumors were graded as negative for cytoplasmic TLR9 expression, as compared with patients whose tumors were strongly immunopositive for cytoplasmic TLR9 (P=0.009)." (PMID 23761830, 2013). "The question that remains, however, is whether TLR9 is a driver or a passenger in prostate cancer." (PMID 23761830, 2013).